CCL2 (C-C motif chemokine ligand 2)
Diseases named in the same sentence as CCL2 in open-access papers (continued):
Sharing a sentence is not in itself a finding about the gene and the disease.
tumor (continued). "Several studies reported the pivotal role of tumor cell- or tumor-associated stroma-derived CCL2, as master regulator of monocyte/macrophage recruitment to the tumor site." (PMID 28197019, 2017). "Consistent with the slightly elevated CCL2 levels in tumour-bearing Δp/np mice, RAF1-deficient hepatocytes expressed higher basal and LPS-induced levels of this chemokine." (PMID 28000790, 2016). "In vivo CCL2 gene silencing inhibited primary tumor growth and metastasis, associated with a reduction in cancer stem cell renewal and recruitment of M2 macrophages." (PMID 27283985, 2016). "This is associated with increases in circulating T regulatory cells (Tregs) and myeloid-derived suppressor cells (MDSCs), which are recruited to tumours by chemokines such as CCL2 released by tumour-associated microglia and macrophages." (PMID 27918464, 2016). "In contrast, disruption of Ccr2, which encodes CCL2’s sole signaling receptor, accelerated tumor development, shortened host survival, and mobilized EPCs." (PMID 27820834, 2016). "Disruption of Ccl2 was associated with a decrease in the development and mobilization of endothelial precursor cells (EPCs) which can contribute to tumor neovascularization." (PMID 27820834, 2016). "Through a novel gene silencing approach, we show that targeting CCL2 expression inhibits tumor progression associated with a reduction in cancer stem cells and M2 macrophages." (PMID 27283985, 2016). "As elevated expression of CCL2 in tumors is associated with increased tumor growth and poorer overall survival through an increase in macrophage infiltration, the expression of intra-tumoral MCP-1 (Ccl2) and emr1 (Adgre1) was examined." (PMID 27448965, 2016). "Elevated serum CCL2 is associated with increased tumor macrophage infiltration, angiogenesis, and shortened survival." (PMID 27820834, 2016). "CCL2 is known to promote M2 phenotype of tumor-associated macrophage polarization leading to angiogenic activation through VEGF-A production." (PMID 27166185, 2016). "Instead, CCL2 gene silencing lead to increased tumor cell necrosis and autophagy, associated with a reduction in the number of cancer stem cells and recruitment of M2 macrophages." (PMID 27283985, 2016). "CCL2 recruits inflammatory leukocytes (such as tumour-associated macrophages) in the tumour microenvironment and facilitates cancer cell progression." (PMID 27027349, 2016). "CCL2 has been implicated in macrophage recruitment on the tumor site and enhanced cancer progression." (PMID 27367029, 2016). "Another key chemokine that has been implicated in macrophage recruitment to the tumor microenvironment is CCL2/MCP-1." (PMID 26884646, 2016). "CCL2, an inflammatory chemokine, is closely connected with tumor associated macrophage (TAM) infiltration and cancer progression." (PMID 26294325, 2015). "On the other side, macrophage depletion caused by CCL2 inhibition was found to restrict tumor development." (PMID 24416340, 2014). "For example, CCL2 is known to drive the differentiation of macrophages towards the M2 phenotype, typically associated with a tumor progression." (PMID 24970800, 2014). "CCL2 is a chemokine that functions as a chemoattractant, facilitating angiogenesis through the recruitment of tumor associated macrophages (TAMs)." (PMID 24932473, 2014). "The CCL2 likely exerts its protumorigenic effects through recruitment of tumor-associated macrophages and angiogenesis." (PMID 24591761, 2014). "The expression of CCL2, which is associated with infiltration and migration of tumor-related macrophages, has been demonstrated in several tumor tissues including CRC." (PMID 25515685, 2014). "Our data are reminiscent of what observed in a recent report in which down-regulation of CCL2 after treatment with the BRAF inhibitor PLX4720 was associated with reduced tumor growth." (PMID 24980831, 2014).
tumor (continued). "Inflammatory cytokines (e.g., CXCL1, CXCL2 and CCL2), involved in recruiting tumour-associated macrophages (TAMs), were importantly shown to be produced by these cells to further advance tumourigenesis." (PMID 24216702, 2013). "Tumor cells express CCL2/MCP-1 (C-C-motif ligand 2/monocyte chemotactic protein-1), and thus, tumor-associated macrophages (TAMs) are recruited, resulting in an inflammatory response." (PMID 21941547, 2012). "CCL-2 produced by tumor cells and tumor associated cells attracts and shapes myeloid cells and interferes with osteoclasts in bone- metastatic disease." (PMID 22176642, 2011). "In another study, tumor cells transfected with CCL2 showed decreased metastasis due to increased infiltration of macrophages and susceptibility of tumor cells to lysis by infiltrating macrophages." (PMID 21450101, 2011). "Colorectal and pancreatic carcinoma cells are known to secrete CCL2 which is associated with increased tumor infiltration of macrophages." (PMID 21450101, 2011). "In another study, transfection of mouse CT-26 CRC cells with CCL2 gene resulted in decreased metastasis and increased susceptibility of tumor cells to macrophage lysis." (PMID 21450101, 2011). "Amino-phthalimides down-regulated the expression of CCL2, which is implicated in tumor metastasis and angiogenesis." (PMID 20525221, 2010). "CCL2 levels have been shown to be associated with severity or progression in a number of tumor types." (PMID 20368123, 2010). "Here, we find that the activated mast cells remodel tumor inflammatory microenvironment by upregulating CCL2, IL-10 and IL-13, which are associated with the migration and function of MDSCs, respectively." (PMID 20111717, 2010). "In this issue of the JCI, Sun, Zhang, and colleagues identified nonhistone ENSA-K63 lactylation as a critical regulator that inactivates PP2A, activates STAT3/CCL2 signaling, recruits tumor-associated macrophages (TAMs), and suppresses cytotoxic T cell activity." (PMID 40166931, 2025). "Moreover, further experiments suggested that this progression depended on CCL2 for its function in tumor‐associated macrophages." (PMID 39947253, 2025). "Long before it becomes a metastatic site, the primary tumor and stromal cells, such as cancer-associated fibroblasts (CAFs), produce CCL2 that stimulates the recruitment of monocytes and Mo-MDSCs to the PMN and their differentiation towards pro-tumorigenic macrophages." (PMID 40427136, 2025). "Furthermore, exosomal CMTM6 activates the mTOR signaling pathway in tumor-associated macrophages, enhancing CCL2 secretion, which further promotes M2a polarization and accelerates tumor metastasis." (PMID 40761779, 2025). "Moreover, CCL2 has been shown to promote the polarization of tumor-associated macrophages (TAMs), which exert immunosuppressive effects by inhibiting T cell activation and fostering angiogenesis." (PMID 41200178, 2025). "Additionally, PTEN loss increases secretion of CCL2, attracting myeloid cells that enhance the survival and proliferation of brain metastatic tumor cells." (PMID 40016470, 2025). "Transcriptional profiling of tumor-associated macrophages isolated from treated tumors revealed an upregulation of gene networks linked to immune activation and a concomitant decrease in CCL2 expression, consistent with reduced infiltration of tumor-associated macrophages into the tumor bulk." (PMID 40732256, 2025). "PIPKIγ has several functions in malignancies, such as controlling the Warburg Effect in colon cancer, recruiting tumor-associated macrophages by modulating the expression of CCL2, and controlling the expression of PD-L1 in tumor cells and colorectal cancer cells." (PMID 40136426, 2025). "CCL2 rs1024611 SNP may also be associated with the occurrence and development of cervical cancer, deep stromal invasion, large tumor diameter, and parametrial invasion." (PMID 41341593, 2025).
tumor (continued). "The expression of CCL-2 and CSF-1 by reactive astrocytes is particularly significant, as it appears to regulate the recruitment of tumor-associated macrophages and their subsequent reprogramming into a phenotype that supports HGG growth and invasion (Perelroizen and others 2022)." (PMID 39066464, 2025). "Elevated CCL2 secretion by tumor cells facilitates tumor-associated TAM recruitment to the TME." (PMID 39883522, 2025). "Silibinin exerts multifaceted anticancer effects by suppressing PD-L1 expression through the inhibition of JAK/STAT3 signaling and MUC1-C interaction, attenuating NF-κB-driven inflammation, and downregulating CCL2-mediated recruitment of tumor-associated macrophages (TAMs)." (PMID 40650040, 2025). "Consequently, elevated CCL2 secreted by tumor cells facilitates tumor-associated macrophage (TAM) recruitment to the TME." (PMID 39883522, 2025). "The cytokine CC ligand 2 (CCl2), a chemokine associated with tumor progression in a variety of cancer types, also known as human monocyte chemotactic protein 1 (MCP-1), is a member of the CC chemotactic family and a known chemokine that recruits monocytes/macrophages to sites of inflammation." (PMID 39531472, 2024). "Additionally, EHF proficiently recruits and activates tumor‐associated macrophages via the CCL2/CCR2 axis, leading to tumor microenvironment remodeling." (PMID 38741887, 2024). "It is known that tumor‐associated MΦs secrete CCL2, which promotes EMT in cancer cells." (PMID 37716915, 2024). "Therefore, migration toward target cells is very important, and this process is regulated and guided by chemokines such as CXCL12, CXCL10, and CCL2, produced by tumor cells, tumor-associated macrophages, and fibroblasts." (PMID 39796680, 2024). "Another study showed that the activation of YAP in tumor-initiating cells (TICs) recruits TIC-associated macrophages via the induction of C-C motif chemokine ligand 2 (CCL2) and colony-stimulating factor 1 (CSF1), suppressing the immune clearance of TICs to promote tumorigenesis." (PMID 38566194, 2024). "Moreover, EHF significantly recruited and activated tumor‐associated macrophages (TAMs) through the C‐C motif chemokine 2/C‐C chemokine receptor type 2 (CCL2/CCR2) axis, thereby remodeling the tumor microenvironment." (PMID 38741887, 2024). "Furthermore, CCL2 can enhance the tumoricidal capacity of neutrophils and interact with tumour‐associated macrophages, inducing the transition of non‐tumorigenic breast epithelial cells to an invasive phenotype." (PMID 39706820, 2024). "Sorafenib also mediated the infiltration of tumor-associated neutrophils (TANs) in hepatocellular carcinoma patients and animal models, while TANs further promoted more intratumoral macrophages and T-regulatory (Treg) cells through secreting CCL2 and CCL17." (PMID 38787372, 2024). "Similarly, tumor-associated macrophage CCL2 was reported to facilitate the recruitment of PMN–MDSCs and M-MDSCs in a renal tumor study." (PMID 38360737, 2024). "In vivo, the combination treatment could remodel the immune landscape, reducing levels of CCL2 cytokine, which has been linked to immune suppression and poor prognosis, and increasing the levels of cytokines that enhance anti-tumor responses, such as CCL6." (PMID 38160212, 2024). "Additionally, β2-AR/CCL2 activation was associated with decreased PD-L1 resistance and reduced tumor burdens in eustress mouse models subjected to exercise with running wheels." (PMID 38689092, 2024). "The directed activation of neutrophils towards a suppressive phenotype leads to overall immunosuppression as these tumor-associated neutrophils inhibit T cell and NK cell functions, produce chemokines (CCL2, CCL3, and CCL5), and promote tumor growth and angiogenesis." (PMID 39768223, 2024). "Moreover, NO-induced nitration of the chemoattractant CCL2 can cause successfully migrated T cells to remain trapped in the tumor stroma." (PMID 39211039, 2024).
tumor (continued). "In addition to inducing apoptosis in human ovarian cancer cells, kumatakenin reduces tumor cell expression of CCL2 and CCL5 – both implicated in macrophage recruitment, cancer progression and metastasis." (PMID 39555068, 2024). "Previous studies have revealed that CCL2 may cause tumor infiltration by tumor-infiltrating lymphocytes, which have an anticancer effect, consistent with our results." (PMID 38245792, 2024). "This analysis revealed a loss of the immune-related molecule CCL2 over time, contributing to a “cold” tumor microenvironment, and an increase in metastasis-associated molecules like MITF, KIT, and VIM, suggesting a potential transition to a mesenchymal phenotype." (PMID 38975339, 2024). "Indeed, cisplatin increased oxPAPC level in tumour tissues of WT mice, CCL2−/− and LTB4R−/− mice, but caused increased infiltration of Ly6Chigh monocytes and neutrophils only in WT LL2‐bearing mice." (PMID 37905494, 2024). "Tumor associated macrophages marker genes played a crucial role in tumor process, for example, high expression CCL2 in macrophages could promote HNSCC invasion and metastasis." (PMID 37065499, 2023). "Tumor-associated macrophages are mostly recruited by CCL2 released from tumors and their stroma." (PMID 37762054, 2023). "Thus, SASP-associated CCL2 is both necessary and sufficient to drive NK cell infiltration and potentiate NK cell-mediated tumor control in PDAC following T/P-induced senescence." (PMID 37142692, 2023). "= 0.357, p = 8.24 × 10−13); tumor-associated macrophage (TAM): CCL2 (cor." (PMID 36983741, 2023). "However, when crossed with EC-Gαs-KO mice to generate inducible endothelium-specific Gαs/CCL2 double-deficient mice (EC-Gαs/Ccl2-dKO) we found that loss of endothelial CCL2 normalized the tumor phenotype of EC-Gαs-KO animals." (PMID 36374225, 2023). "On the other hand, mRNA expression of Ccl2 (macrophage chemotaxis marker), Cd68 (tumor associated macrophages, TAMs), Cd163 (M2 TAMs) and Foxp3 (regulatory T cells, Tregs) markers was greatly increased in LLC control mice, while this increment was less pronounced in 6-thio-dG-treated mice." (PMID 37085672, 2023). "This adaptive PTEN loss in brain metastatic tumor cells led to an increased secretion of the chemokine CCL2, which recruits IBA1-expressing myeloid cells that reciprocally enhanced the outgrowth of brain metastatic tumor cells via enhanced proliferation and reduced apoptosis." (PMID 38020906, 2023). "A potential association between IL-6 and CCL2, secreted by tumor-associated fibroblasts, and high Ki-67 levels was found, speculating how tumor proliferation in PitNETs may be influenced by fibroblasts." (PMID 37958702, 2023). "Tumors in Ccl2-/- mice contained the same total number of TAMs as tumors in WT mice, but Ccl2 disruption was associated with a marked reduction in the numbers of EPCs in the bone marrow and circulation, which may suppress tumor angiogenesis." (PMID 37208442, 2023). "Furthermore, loss of PTEN in brain metastatic tumor cells increased the expression of cytokine chemokine (C‐C motif) ligand 2 (CCL2), which promoted the development of brain metastatic tumor cells." (PMID 35822637, 2023). "The observed reduction in tumor burden and tumor size in TG mice was associated with decreased expression of inflammatory cytokines such as Il-1b, Il-6, Il-17, and Ccl2 in the tumor and tumor-adjacent tissue, as well as a likely reduction in tumor-infiltrating immune cells." (PMID 38090485, 2023). "In many previous studies, CCL2 has been implicated in promoting tumour progression and metastasis." (PMID 37108548, 2023). "For immune cell composition, activation of EGFR signaling could induce CCL2 expression and then elevate the infiltration of tumor-associated macrophages (TAMs) in the TME." (PMID 37759950, 2023).
tumor (continued). "Additionally, our cytokine analysis determined an uplifted level of inflammatory cytokines, such as VEGF, IL-6, and CCL2, that can cause the progression of the tumor and initiate CRS, which limits the treatment and has a negative impact on the outcome." (PMID 37112810, 2023). "The expression of NUPR1 was highly correlated with tumor‐associated macrophage markers including C‐C motif chemokine ligand 2 (CCL2, R = 0.392, p < 0.001), C‐C chemokine receptor type 5 (CCR5, R = 0.323, p < 0.001), CD80 (R = 0.302, p < 0.001), and CD86 (R = 0.381, p < 0.001)." (PMID 36468653, 2023). "Moreover, various SASP factors, including interleukins 1, 6 and 8, as well as chemokines CXCL8 and CCL2 have been associated with accelerated tumor proliferation and invasion in CRC." (PMID 38275386, 2023). "They further showed that activation of STING signaling in tumor cells promoted an induction of the chemokines CCL2 and CCL7 that were associated with immune resistance and was able to be reversed via the incorporation of a CCR2 (CCL2 and CCL7 receptor) antagonist into the formulation." (PMID 37627155, 2023). "Notably, PTEN loss is responsible for the increased release of CCL2 that autocrinally reinforces the migration of tumor cells." (PMID 38293652, 2023). "Cancer-associated fibroblasts (CAFs) recruit macrophages to the tumour site through the expression of chemoattractant signals such as CCL2 and regulate the immune response to tumour cells by driving the polarization of macrophages with pro- or anti-tumorigenic phenotypes." (PMID 37108548, 2023). "Furthermore, FAT4 expression was associated with markers of tumor-associated macrophages, such as CCL2, CD68, and IL-10." (PMID 37735184, 2023). "Compared with shCon-MDA-MB-231, loss of CCL2 significantly delayed tumor growth in vivo." (PMID 36038549, 2022). "CCL2 expression has an oncogenic function by recruiting immune cells such as M2-type Tumor-Associated Macrophages (TAMs) and T-regulatory cells (Tregs), promoting an immunosuppressive microenvironment favorable to tumor progression." (PMID 35046519, 2022). "Moreover, it has been shown that tumor-associated astrocytes can produce CCL2, which helps to maintain the stem-like properties of metastatic MB cells, in addition to being a chemoattractant for TAMs and microglia." (PMID 36291792, 2022). "Generally, tumor cells and tumor-associated stroma are rich sources of CCL2, the ligand for CCR2." (PMID 33603130, 2022). "The CCR2/CCL2 is a known recruitment axis for tumor associated macrophages and highly expressed by TAO1 cells in culture we utilized a CCR2 KO model, which leads to deficiencies in monocyte recruitment into tumors and has been shown reduced tumor macrophages in previous work." (PMID 36700206, 2022). "In addition, tumor-associated neutrophils (TANs) can mediate the intratumoral infiltration of macrophages and regulatory T cells (Tregs) by secreting CCL2, which contributes to HCC progression, metastasis, and prognosis." (PMID 35281057, 2022). "Interestingly, SERPINA3 was positively correlated with TNF and TNF was positively correlated with CCL2, a marker of tumor associated macrophages." (PMID 36406134, 2022). "CCL2 is another tumor-derived chemokine implicated in the early metastatic cascade." (PMID 35954395, 2022). "Indeed, tumor-antigen-specific Tregs were shown to mobilize from the bone marrow toward tumor-associated CCL2 and provide a dominant dampening of the effector response, and in our study, the CAR Tregs migrated to the site of Bw6+ islet." (PMID 35551746, 2022). "Furthermore, in vitro assays have shown CCL2-secreting CAFs (or CAF-0s) attract tumor-associated THP-1 macrophages, while CXCL12-secreting CAFs (or CAF-1s) can attract monocytes and trigger their differentiation into M2-like macrophages." (PMID 36671452, 2022).